NLRP3 (NLR family pyrin domain containing 3)
Diseases named in the same sentence as NLRP3 in open-access papers (continued):
Sharing a sentence is not in itself a finding about the gene and the disease.
intestinal diseases (12 papers, 2018 to 2025). "Future studies to elucidate the NLRP3 inflammasome’s protective and or pathogenic role in intestinal disorders are needed." (PMID 41149694, 2025). "NLRP3 inflammasomes and their downstream signaling molecules have become potential targets for the treatment of various intestinal diseases in chickens." (PMID 38928401, 2024). "It has been reported that pyroptosis is regulated by the NLRP3 inflammasome, and NLRP3-related pyroptosis plays an important role in intestinal diseases." (PMID 38406274, 2024). "In recent years, the role of the NLRP3 inflammasome in intestinal diseases has attracted widespread attention." (PMID 38928401, 2024). "Shaoyao decoction protects against intestinal ulcers by inhibiting the MKP1/NF-κB/NLRP3 pathway-mediated pyrosis." (PMID 38001450, 2023). "When the NLRP3 inflammasome is abnormally activated, various intestinal diseases can be induced." (PMID 38928401, 2024). "Recent studies have testified that NLRP3‐related pyroptosis has involvement in intestinal diseases." (PMID 37506161, 2023). "One study found significant overexpression of NLRP3 in the inflamed gut of SKG mice, and treatment of SKG mice with mcc950, an NLRP3 antagonist, prior to induction of inflammatory disease inhibited the development of intestinal disease and delayed the onset of joint inflammation." (PMID 36275747, 2022). "A devastating intestinal disease in premature infants, NEC, involves excessive inflammation mediated by NLRP3." (PMID 41149694, 2025).
vasculopathy (10 papers, 2020 to 2025). "NLRP3-mediated damage and necrosis of ECs were also found in diseases which are relevant to vasculopathy." (PMID 35974386, 2022). "It suggests a potential function of IL-1β and its activator, NLRP3 inflammasome, in vasculopathy of SSc." (PMID 35974386, 2022). "Collectively, our findings suggest Ap4 as a novel pro-inflammatory mediator capable of inducing IL-1β release in innate immune cells through distinct mechanisms from classical NLRP3 inflammasome activators, shedding light on its potential role in inflammatory diseases and vascular disorders." (PMID 39984847, 2025). "In addition, Pcsk9 knockout inhibits NLRP3 inflammasome signaling in VSMCs and reduces allograft vasculopathy." (PMID 35720337, 2022).
genetic diseases (9 papers, 2012 to 2025). "There is also a group of rare genetic diseases caused by gain-of-function mutations in NLRP3 called cryopyrin-associated periodic syndromes or NLRP3-associated autoinflammatory diseases (NLRP3-AID)." (PMID 40892070, 2025). "Genetic disorders involving activation of NLRP3 inflammasome is associated with various inflammatory disorders." (PMID 22295065, 2012). "While IL-1β secretion from wild-type mouse BMDM was roughly 50% at 20 μM concentration of the 16673-34-0 crossbreed, the effect was markedly blunted in macrophages carrying NLRP3-activating mutations usual of NLRP3-selective genetic disorders like Muckle–Wells." (PMID 34443594, 2021). "Since CAPS is a rare genetic disease, few investigations of NLRP3 inflammasomes had been performed until the link between NLRP3 inflammasomes and sterile inflammation was uncovered." (PMID 29259717, 2017). "Another genetic disorder leading to increased NLRP3 inflammasome activity in the intestine involves an abnormality in the function of tyrosine phosphatase non-receptor 22 (PTPN22), an enzyme that dephosphorylates NLRP3 at Tyr859 (in mice) and Tyr861 (in humans)." (PMID 30455704, 2018).
myopathies (7 papers, 2018 to 2024). "NLRP3 inflammasomes have also been shown to be active in myocytes and are upregulated in degenerating muscles, muscle atrophy, muscle loss and myopathies." (PMID 34199845, 2021). "Altogether, these studies support the role of the NLRP3 inflammasome in inflammatory myopathies and the potential for the development of NLRP3 inflammasome-targeted therapies." (PMID 34199845, 2021). "Similarly to other myopathies, the NLRP3 inflammasome is upregulated in dystrophic mdx muscles and human DMD muscle cells." (PMID 34199845, 2021). "The inflammasome NLRP3 is upregulated in DMD, and its ablation attenuates the dystrophic phenotype, suggesting that NLRP3 inhibitors may have a therapeutic potential for muscle inflammation and myopathies." (PMID 29558930, 2018). "Inflammasome NLRP3 expression is upregulated in DMD skeletal muscle fibers, where it is downregulated by ApN and its anti-inflammatory mediator Mir-711 and attenuates the dystrophic phenotype, suggesting that NLRP3 inhibitors may have therapeutic potential for muscle inflammation and myopathy." (PMID 36405697, 2022). "NLRP3 was significantly overexpressed in muscle biopsies from IBM samples compared to disease controls (p = 0.049), including other inflammatory myopathies." (PMID 37445853, 2023). "We studied, by real-time PCR, the differences in NLRP3 gene expression profiles between three different groups: healthy subjects (control), ALS patients and patients with other myopathies (OMP)." (PMID 33802349, 2021). "Though NLRP3 inflammasome primarily presents in immune and inflammatory cells, emerging evidences have indicated that NLRP3 also appears within muscle cells of DMD and other myopathies." (PMID 36713032, 2023). "Additionally, in the mouse model of valosin-containing protein (VCP) myopathy, MCC950 improved the physical performance of mice by inhibiting the activation of the NLRP3 inflammasome, which has an effective therapeutic potential in the treatment of VCP-related myopathy." (PMID 36405697, 2022). "We found that NLRP3 transcriptional levels were significantly increased in ALS patients’ blood with respect to controls, but not compared to other myopathies." (PMID 33802349, 2021). "Moreover, we could demonstrate an upregulation of NLRP3 in samples of IBM patients, but neither in other idiopathic inflammatory myopathies, nor in muscle dystrophies." (PMID 37445853, 2023).
peripheral neuropathy (6 papers, 2020 to 2025). A disorder affecting the peripheral nervous system. "The pathogenesis of peripheral neuropathy in T2DM rats may be linked to TXNIP/NLRP3 inflammasome pathway activation, indicating the potential of this pathway as a therapeutic target for diabetic peripheral neuropathy (DPN)." (PMID 35845136, 2022). "NLRP3 was increased in primary sensory neurons and macrophages in chemotherapy-induced peripheral neuropathy, inducing mechanical hypersensitivity." (PMID 37614230, 2023). "Investigation of NLRP3 expression in spinal cord of oxaliplatin- and paclitaxel-induced peripheral neuropathy model." (PMID 32973552, 2020). "Assessment of the NLRP3 activation in oxaliplatin induced peripheral neuropathy model in rats treated with MCC950." (PMID 32973552, 2020). "Assessment of mechanical allodynia of mice in a bortezomid-induced peripheral neuropathy model and the intrathecal treatment with NLRP3 siRNA." (PMID 32973552, 2020). "Moreover, eicosapentaenoic acid alleviated the hyperalgesia in oxaliplatin-induced peripheral neuropathy mice by inhibiting NETs formation and then abolishing NLR family pyrin domain containing 3 (NLRP3) inflammasome activation." (PMID 37581321, 2024).
gastrointestinal disease (5 papers, 2021 to 2026). A disease that occurs in the gastrointestinal system, excluding the hepatobiliary system. "In conclusion, DCPH alleviates gastric mucosal injury via regulating autophagy and targeting TLR4/NF-κB/NLRP3, thereby offering insights for the treatment of gastrointestinal diseases." (PMID 41982492, 2026). "As a result, a review paper is demanded to review and summarize the previous and latest studies on the role and mechanisms of NLRP3 inflammasome in pathogenesis and progression of inflammation-related gastrointestinal diseases." (PMID 40860651, 2025). "Further research is needed to develop effective NLRP3 inflammasome-targeted therapeutic agents for managing inflammation-related gastrointestinal diseases." (PMID 40860651, 2025). "Potential pharmacological mechanisms of NLRP3 inflammasome inhibitors in inflammation-related gastrointestinal disease treatment." (PMID 40860651, 2025). "Beyond the variability in experimental factors, studies on gastrointestinal diseases highlight a role for NLRP3 in maintaining epithelial barrier integrity, which may also be relevant to the airways." (PMID 41394833, 2025). "This study aims to provide scholars engaged in research on gastrointestinal diseases with new directions for developing more effective therapeutics for inflammation-related gastrointestinal diseases by investigating the NLRP3 inflammasome’s role in these conditions." (PMID 40860651, 2025).
autosomal dominant disease (4 papers, 2013 to 2025). Autosomal dominant form of disease. "NLRP3-AID is a group of autosomal dominant diseases that is defined by a mutation in the NLRP3 (nucleotide-binding domain, leucine-rich repeat family, pyrin domain containing 3) gene located on chromosome 1q44." (PMID 32019685, 2020). "NLRP3-AID and NLRP12-AID are autosomal dominant disease and patients share similar phenotypes, including cold-induced urticaria/inflammatory disease and neurosensory hearing loss." (PMID 38343435, 2023).
adenocarcinoma (3 papers, 2022 to 2024). A common cancer characterized by the presence of malignant glandular cells. "In addition, studies have shown that the overexpression of miR-223 in human adenocarcinoma alveolar basal epithelial cells can reduce LPS-induced Caspase-1, IL-1β, and IL-18 levels by targeting NLRP3." (PMID 38448875, 2024). "It is suggested that NLRP3 inflammasome-induced cellular pyroptosis may play a role in promoting adenocarcinoma growth." (PMID 37081882, 2023). "In addition, it was found that the NLRP3 inflammasome could enhance phosphorylation of Akt, ERK1/2, and CREB to promote adenocarcinoma proliferation by activating caspase-1 and producing mature IL-1β and IL18." (PMID 37081882, 2023).
benign tumours (3 papers, 2016 to 2024). "The importance of NLRP3 inflammasome has been implied in many diseases of the heart, lung, liver, and kidney." (PMID 26866373, 2016).
digestive system diseases (3 papers, 2022 to 2025). "The NLRP3 inflammasome has a dual role as a protective or injurious cause for various gastrointestinal disorders, such as IBD and NEC." (PMID 41149694, 2025). "Abnormal levels of the NLRP3 inflammasome and pro-inflammatory cytokines are linked to several gastrointestinal disorders, such as IBD." (PMID 41149694, 2025). "Excessive initiation of the NLRP3 inflammasome, which is associated with the severity of digestive disease, has been found in patients and animal models’ blood and tissues, demonstrating that NLRP3 inflammasome plays a vital role in the development of digestive disorders." (PMID 36389791, 2022). "Several studies have shown the role of the NLRP3 inflammasome in the pathogenesis of digestive diseases." (PMID 41149694, 2025). "This review also aims to contribute to the existing body of knowledge by presenting new findings, insights, methodologies, and perspectives on the role of NLRP3 inflammasomes in pediatric digestive system diseases." (PMID 41149694, 2025). "Although we learned that NLRP3 plays a key part in the progression of digestive system diseases, there are still related mechanisms that remain undefined." (PMID 38182564, 2024). "Above all, deep interrogation of the NLRP3 inflammasome is a better insight of the pathomechanism of digestive diseases." (PMID 36389791, 2022). "Taken together, this paper offers an integrated overview of priming and activation of the NLRP3 inflammasome, and its role in the pathogenesis of digestive system diseases in recent years, including clinical and experimental evidence." (PMID 36389791, 2022). "Small‐molecule chemical drugs able to inhibit NLRP3 activation in animal models of digestive diseases." (PMID 36389791, 2022). "NOD-like receptor family pyrin domain containing 3 (NLRP3) inflammasome is the most characteristic multimeric protein complex and is involved in a wide range of digestive diseases as intracellular innate immune sensors." (PMID 36389791, 2022). "In this context, we provide a comprehensive review of NLRP3 inflammasome priming and activation in the pathogenesis of digestive diseases, including clinical and preclinical studies." (PMID 36389791, 2022). "Deep discussion of NLRP3 inflammasome is aimed at a better understanding of digestive diseases and provides an opportunity to prevent and treat these diseases." (PMID 36389791, 2022). "The multilevel fine regulation of NLRP3 inflammasome pathway contributes to the treatment of digestive diseases and facilitates the research and development of precision therapeutic targets." (PMID 36389791, 2022). "The discovery of NLRP3 inflammasomes has enriched our knowledge of the pathogenesis of multiple digestive diseases." (PMID 36389791, 2022). "Biologics able to inhibit NLRP3 inflammasome in digestive diseases." (PMID 36389791, 2022). "Phytochemicals targeting on NLRP3 inflammasome in animal models of digestive diseases." (PMID 36389791, 2022).
gynecological diseases (3 papers, 2020 to 2026). "NLRP3 inflammasome is closely associated with various gynecological diseases, especially in gynecological-oncology conditions." (PMID 33584639, 2020). "We comprehensively summarize the molecular mechanisms of inflammasome activation-particularly NLRP3, AIM2, and IFI16-and their dual roles in inflammatory injury and immune regulation across gynecological diseases." (PMID 42079573, 2026).
neuromuscular disease (2 papers, 2021 to 2023). "A growing body of evidence suggests that dysregulation, impairment or aberrant NLRP3 inflammasome signaling leads to the initiation and exacerbation of pathological processes associated with neuromuscular diseases." (PMID 34199845, 2021). "In this review we focus primarily on the involvement of the NLRP3 inflammasome in neuromuscular diseases." (PMID 34199845, 2021). "In addition, we also examine whether therapeutic targeting of the NLRP3 inflammasome components is a viable approach to alleviating the detrimental phenotype of neuromuscular diseases and improving clinical outcomes." (PMID 34199845, 2021). "Thus, iPSC technologies could provide efficient models for investigating the NLRP3 inflammasome in neuromuscular diseases as well as developing novel therapeutics targeting its assembly in these disorders." (PMID 34199845, 2021). "Thus, these rare neuromuscular diseases could indeed benefit from NLRP3 inflammasome-targeted treatments." (PMID 34199845, 2021).
skeletal muscle disorder (2 papers, 2021 to 2025). A disease involving the skeletal muscle tissue. "The NLRP3 inflammasome unequivocally plays a key pathological role in the development and progression of several skeletal muscle disorders." (PMID 34831246, 2021).
animal disease (1 paper, 2021). "These GC-VLNs potently inhibited NLRP3 inflammasome-mediated inflammation in cell culture and animal disease models." (PMID 34646372, 2021).
CNS tumors (1 paper, 2022). "Beta-hydroxybutyrate can inhibit NLRP3 inflammasome assembly and NLRP3-mediated cytokine production, resulting in reduced inflammatory markers in CNS tumors." (PMID 36145228, 2022).
musculoskeletal system diseases (1 paper, 2024). "Additional evidence suggests that ubiquitination or deubiquitination modifications can exacerbate musculoskeletal diseases by promoting conductance in the NLRP3 inflammasome upstream pathway." (PMID 38193803, 2024). "A study has reported that ubiquitination or deubiquitination modifications indirectly inhibit NLRP3 inflammasome activation and reduce inflammatory responses in musculoskeletal system diseases." (PMID 38193803, 2024). "The NLRP3 inflammasomes are vital mediators in the inflammatory cascade response, significantly impacting the progression of various inflammation-related diseases, such as diabetic complications, NDDs, musculoskeletal diseases, and IBD." (PMID 38193803, 2024). "However, there is currently a relative lack of literature focusing on the application of NLRP3 inflammasomes in the clinical treatment of musculoskeletal diseases, with future research needed to explore its mechanism of action." (PMID 38193803, 2024).
neoplastic disorders (1 paper, 2024). "Numerous studies have summarized the role of NLRP3 inflammasome-mediated pyroptosis in various diseases, including cardiovascular, neurological, respiratory, hepatic, renal, intestinal, metabolic, autoimmune, and neoplastic disorders." (PMID 39834371, 2024).
NLRP3 also shares sentences with these, for which no sentence is quoted: acute myocardial infarction (36 papers); chronic periodontitis (15); asbestosis (13); idiopathic pulmonary fibrosis (13); cognitive disorder (12); Allergy (11); cardiac arrhythmias (8); Candidiasis (7); pseudogout (7); acute cystitis (6); corneal ulcer (6); end-stage renal disease (6); Glomerular sclerosis (5); interstitial lung disease (5); juvenile idiopathic arthritis (5); viral diseases (5); Blau syndrome (4); essential hypertension (4); Hyper IgD syndrome (4); Hyperinsulinemia (4); hypertrophy (4); primary immunodeficiencies (4); prostatitis (4); Atherosclerotic lesion (3); autoimmune uveitis (3); Azoospermia (3); blood cancers (3); Familial cold-induced autoinflammatory syndrome (3); Gaucher disease (3); Gliosis (3).
A further 268 diseases each share a sentence with NLRP3 in 3 papers or fewer.